GOLGA7 (golgin A7)
Description:
May be involved in protein transport from Golgi to cell surface. The ZDHHC9-GOLGA7 complex is a palmitoyltransferase specific for HRAS and NRAS.
Synonyms: GCP16; HSPC041; GOLGA3AP1; GOLGA7A
Tractability: Small molecule: a structure with a bound ligand is known. Antibody: its Gene Ontology location is reachable by antibodies, with high confidence. PROTAC: ubiquitination databases record sites on it; its protein half-life has been measured.
Gene: Protein-coding gene on chromosome 8 (41,488,200 to 41,511,095, forward strand). Ensembl gene ENSG00000147533.
Subcellular location: Golgi apparatus membrane
Pathways (Reactome):
Disease: Maturation of spike protein
Immune System: Neutrophil degranulation
Signal Transduction: RAS processing
Gene Ontology:
Molecular function: protein binding
Biological process: Golgi to plasma membrane protein transport; Golgi to plasma membrane transport; post-translational protein modification; peptidyl-L-cysteine S-palmitoylation; protein targeting to membrane
Cellular component: extracellular exosome; Golgi membrane; Golgi stack; palmitoyltransferase complex; extracellular region; tertiary granule lumen
Homologues: Orthologues: dog GOLGA7 (100% identical), mouse Golga7 (99% identical), pig GOLGA7 (99% identical), chimpanzee GOLGA7 (99% identical), guinea pig GOLGA7 (99% identical), rat Golga7 (91% identical), tropical clawed frog golga7 (88% identical), zebrafish golga7 (80% identical), rabbit GOLGA7 (74% identical), macaque GOLGA7 (70% identical), Drosophila melanogaster CG5447 (53% identical), Caenorhabditis elegans Y57G11C.33 (36% identical). Paralogues in human: GOLGA7B (75% identical).
Diseases named in the same sentence as GOLGA7 in open-access papers:
GOLGA7 is named in the same sentence as 14 diseases in open-access papers, as found by Europe PMC text mining. Sharing a sentence is not in itself a finding about the gene and the disease. The quoted sentences say what the papers report.
leukemia (2 papers, 2024 to 2025). A malignant (clonal) hematologic disorder, involving hematopoietic stem cells and characterized by the presence of primitive or atypical myeloid or lymphoid cells in the bone marrow and the blood. "Based on the significant efficacy of Golga7 loss in Nras‐driven leukemia, it seems that interfering with the association of GOLGA7 within RAS‐PAT complex would be a sensible strategy for targeting this non‐enzymatic protein." (PMID 40091521, 2025). "Also, NrasG12D/G12D; Mx1‐Cre+; Golga7HET mice had prolonged OS (median, 124 days; P = 0.0061) when compared to Golga7WT counterparts, suggesting a moderate dose‐dependent inhibitory effect of Golga7 loss on NrasG12D‐driven leukemia development." (PMID 40091521, 2025). "To evaluate the effect of Golga7 loss on the development of NrasG12D‐driven leukemia in vivo, we initially created a conditional Golga7 (Gene ID: 57 437) gene knockout mouse line based on Cre‐loxP recombination system by employing CRISPR/Cas9 gene editing technology." (PMID 40091521, 2025). "A recent genome-wide CRISPR screening study identified GOLGA7 as a NRAS co-dependent gene in leukemia cell lines with or without NRAS mutation." (PMID 38317235, 2024). "Our study shows that GOLGA7 serves as a safe and effective therapeutic target for NRAS‐driven leukemia." (PMID 40091521, 2025). "We also examined the impact of constitutive Golga7 knockout on normal development and physiology in mice to ascertain whether GOLGA7 serves as a safe and effective therapeutic target for NRAS‐driven leukemias." (PMID 40091521, 2025). "Compared to the control group, Golga7 knockout Ba/F3-N group showed lower percentage of GFP-positive cells and white blood cell (WBC) counts in the peripheral blood 10 days after transplantation, indicating less leukemia burden." (PMID 38317235, 2024).
glioma (1 paper, 2021). A benign or malignant brain and spinal cord tumor that arises from glial cells (astrocytes, oligodendrocytes, ependymal cells). "Linghui Zhou found that rs11337 (G > T) in GOLGA7 is related to survival of glioma patients." (PMID 34970268, 2021).
myeloid leukemia (1 paper, 2025). A clonal proliferation of myeloid cells and their precursors in the bone marrow, peripheral blood, and spleen. "Knocking out Golgin subfamily A member 7 (Golga7), an accessory protein of RAS palmitoyltransferases, through a conditional gene editing approach drastically suppresses the development of myeloid leukemia induced by the activation of NrasG12D/G12D knock‐in alleles in mice." (PMID 40091521, 2025).
myeloproliferative neoplasm (1 paper, 2025). A clonal hematopoietic stem cell disorder, characterized by proliferation in the bone marrow of one or more of the myeloid (i.e., granulocytic, erythroid, megakaryocytic, and mast cell) lineages. "Loss of Golga7 in adult mice effectively suppresses NrasG12D‐driven myeloproliferative neoplasm by disrupting its PM localization and impairing subsequent MAPK signaling, without affecting normal hematopoiesis or causing detectable toxicity, although it leads to embryo lethality." (PMID 40091521, 2025). "Herein, we used a Golga7 conditional knockout (KO) mouse line to assess the effects of Golga7 on the development and progression of NrasG12D‐mutant CMML‐like myeloproliferative neoplasm (MPN)." (PMID 40091521, 2025).
cancer (5 papers, 2021 to 2025). A tumor composed of atypical neoplastic, often pleomorphic cells that invade other tissues. "The mislocalization of NRAS was similar for all variants of NRAS tested, indicating that the requirement of GOLGA7 for PM localization of NRASG12D applies to commonly mutated NRAS in cancer." (PMID 38317235, 2024). "Remarkably, depleting GOLGA7 effectively inhibits cell proliferation in multiple NRAS-mutant cancer cell lines and attenuates NRASG12D-induced oncogenic transformation in vivo." (PMID 38317235, 2024). "Additionally, we found that GOLGA7 is essential for the proliferation and signaling of cancer cells harboring oncogenic NRAS." (PMID 38317235, 2024). "For example, GOLGA7, ITPK1, and NPRL3 were correlated with increased drug resistance of cancer cells to Dasatinib, Zoledronate, PF-06463922, Brigatinib, LDK-378, Vinorelbine, Carfilzomib, and Bortezomib, respectively." (PMID 34970268, 2021). "The small molecule caspase independent lethal 56 (CIL56) induces a unique form of nonapoptotic cancer cell death that is promoted by a complex formed between zDHHC palmitoyltransferase 5 (ZDHHC5) and an accessory protein, golgin A7 (GOLGA7, also known as GCP16)." (PMID 40930250, 2025).
tumor (2 papers, 2007 to 2021). "The results showed that the expression levels of CORO1B, GOLGA7, PCSK4, ST6GALNAC4, and ZSWIM1 in normal tissues were significantly higher than those in tumor tissues, which were similar to the trends detected in the TCGA dataset." (PMID 34970268, 2021). "GOLGA7, ITPK1, and ST6GALNAC4 genes had lower expression in tumor tissues than in healthy persons (p < 0.05) by means of Wilcoxon signed-rank test." (PMID 34970268, 2021).
infection (1 paper, 2025). The state of being infected such as from the introduction of a foreign agent such as serum, vaccine, antigenic substance or organism. "For the CSDE1 KO and GOLGA7 KO cells, an intermediate CHIKV replication phenotype was observed: CHIKV RNA abundance increased over the course of the infection time course, but it remained well below the levels measured in the NT control cells." (PMID 41372121, 2025).
nervous system disease (1 paper, 2020). "For instance, in OPC protein–protein interaction (PPI) network, proteins involved in Golgi vesicle transport (such as Vamp3, Golga7, Vti1b and Snx1), Cell redox homeostasis (such as Tnx2 and Gsr), nervous system disease (such as Got1, Gm2a, Apoe and Cst3) and other functions were identified." (PMID 32974003, 2020).
GOLGA7 also shares sentences with these, for which no sentence is quoted: breast carcinoma (1 paper); glioblastoma (1); heart failure (1); lung carcinoma (1); viral infection (1); X-linked intellectual disability (1).